IL4 (interleukin 4)
Diseases named in the same sentence as IL4 in open-access papers (continued):
Sharing a sentence is not in itself a finding about the gene and the disease.
dengue (30 papers, 2008 to 2025). "In the literature, IL-1β elevations in dengue patients align with inflammasome activation during infection, and meta-analyses/studies show significant IL-4 and IL-9 increases in acute dengue, consistent with our Th2-associated signals." (PMID 41346606, 2025). "It has been previously shown that pre-treatment of human monocytes with IL-4 or IL-13, increases their susceptibility to dengue virus infection in vitro." (PMID 22574162, 2012). "We further investigated if IL-4 treatment of the two monocyte subsets differentially affects their susceptibility to dengue virus infection." (PMID 22574162, 2012). "Importantly, this may also have in vivo relevance in the context of dengue pathogenesis, as since inflammatory skin conditions caused by mosquito bites are accompanied by secretion of IL-4 that leads to enhancement of infection and cytokine response." (PMID 29020083, 2017). "We showed that IFN-α, IFN-γ, TNF-α, IL-6, MCP-1, IL-2, IL-4, and IL-10 production was higher in patients with dengue than in those with AFI." (PMID 38003826, 2023). "Nevertheless, a Th2 profile leads to the secretion of cytokines, such as IL-4, IL-10, and IL-13, which stimulate B cells to secrete antibodies and are more frequent in dengue patients presenting hemorrhagic disease." (PMID 38003826, 2023). "While the higher serum level of IFN-γ and IL-4 have been previously observed in severe dengue patients, the cellular source of these cytokines especially IFN-γ are believed to be T cells." (PMID 34079535, 2021). "In dengue severity, Th1 cytokines GM-CSF and IFNγ antagonize Th2 cytokines IL-10 and IL-4, respectively, for the progression towards DHF/DSS." (PMID 34447698, 2021). "A number of functional pathways showed centrality differences between the two networks including genes responding to both GM-CSF and IL-4, which had a higher centrality value in an antibody-mediated vs. receptor-mediated Dengue network." (PMID 31527878, 2019). "We found comparable levels of IL-4 between Dengue patients and control groups, suggesting the involvement of IL-9 and -17 in Dengue virus infection." (PMID 22363824, 2012). "We observed that cytokine concentrations of IL-1β, IFN-γ, IL-4, IL-6, IL-7, IL-13 and GM-CSF were significantly increased during severe dengue as compared to mild dengue, while MIP-1β levels are higher in mild dengue." (PMID 18578883, 2008). "In contrast, during convalescent DENV infection, the mean levels of IFN-γ, CXCL10, IL-4, and IL-10 remained relatively high, suggesting that the sustained interplay of Th1, Th2, and Treg may be needed for dengue control in this setting." (PMID 37235332, 2023). "IL-4 is said to trigger Th2-type response and is least studied in dengue pathology." (PMID 34447698, 2021). "Generally, TNF-α, as well as IL-4, IL-6, IL-8, and IL-10, are increased in dengue patients." (PMID 33072626, 2020). "IL-1β, IFN-γ, IL-4, IL-6, IL-13, IL-7 and GM-CSF were significantly increased in patients with severe clinical manifestations (severe dengue) when compared to mild disease forms (mild dengue)." (PMID 18578883, 2008). "•Elevated IL-8, IL-10, IL-6, GM-CSF, MCP-1, IL-13, and IL-4 and decreased IL-12, MIP-1β on the third day after symptom onset is predictive of severe dengue." (PMID 38176525, 2024). "Our findings reveal a distinct cytokine profile (elevated IL-8, IL-10, IL-6, GM-CSF, MCP-1, IL-13, and IL-4 and decreased IL-12, MIP-1β) on the third day after symptom onset is predictive of severe dengue in secondary dengue infection." (PMID 38176525, 2024). "Serum concentrations of IL-2, IL-4, IL-6, IFN-γ, TNF-α, IL-17, and IL-10 were determined in dengue patients at 6 or 7 days of fever onset and were compared with values obtained in a group of healthy controls." (PMID 28827898, 2017).
dengue (continued). "By using multiplex immunoassay, we compared host cytokine profiles between acute CHIKV and DENV infections by analysing serum cytokine levels of IL-1α, IL-4, IL-5, IL-8, IL-13, RANTES, MCP-3, eotaxin, PDGF-AB/BB, and FGF-2 from the sera of acute chikungunya and dengue fever patients." (PMID 34215212, 2021). "Similarly, in dengue severity, DENV-2 shows significant decrease of IL-4 in DSS than DHF and control." (PMID 34447698, 2021). "We did not observe significant production of TNFα, IL-10, IL-4, IL-13, IL-17 by dengue NS3-specific T cells, suggesting a different source for these cytokines in the serum." (PMID 23209731, 2012). "Our first priority was to compare the levels of IL-1b, IL-2, IL-4, IL-6, IL-8, IL-10, IL-12p70, IL-17A, IL-33, CD14, CD54, CD62E, CD62L, CD62p, CD106, CD121b, CD154, CD178, GM-CSF, IFN-g, MIF, ST2 and TNF in plasma samples of dengue group, OF group and Healthy group." (PMID 33809042, 2021). "Without stimulation, a small amount of IFN-γ and IL-4 could be detected in iNKT cells from some of the acute dengue-infected patients." (PMID 24945350, 2014). "In these studies, IL-1ß, IFN-γ, IL-4, IL-6, IL-13, IL-7, GM-CSF (Granulocyte-macrophage colony-stimulating factor), MIF (macrophage migration inhibitory factor), IL-10 along with several other cytokines have been found to be elevated in patients with DHF when compared to dengue fever (DF)." (PMID 23883139, 2013). "However, as the level of IL-4 was not increased in the plasma of Dengue patients, our findings suggest the independent involvement of IL-9 secreted by Th2 cells in Dengue virus infection." (PMID 22363824, 2012). "Many studies have investigated the cytokines patterns in serum samples in patients with DHF and these studies have shown that TNFα, IL-6, IL-10, IL-1β, IFN-γ, IL-4, IL-13, IL-7, GM-CSF, MIF, along with several other cytokines were elevated in patients with DHF when compared to dengue fever (DF)." (PMID 23209731, 2012).
fungal infections (29 papers, 2012 to 2025). "Exogenous supplementation of recombinant IL-4 to mice increases susceptibility to invasive fungal infections, again suggesting the deleterious effects of Th2 responses." (PMID 38787374, 2024). "Traditionally, T helper 1(TH1) produces IFN-γ to provide immunity against fungal infection but IL-4 produced by TH2 increases the susceptibility to infection." (PMID 35059222, 2022). "Therefore, correcting the imbalance of IL-2 and IL-4 caused by fungal infection may contribute to the restoration of local immune homeostasis." (PMID 35295335, 2022). "Anti-inflammatory cytokines such as IL-3, IL-4, IL-5, IL-9, IL-10, and IL-13 were also induced within 3 h of fungal infection in all three groups of mice and remained high up to the 7th day period." (PMID 38783167, 2024). "Further, a significant variation in IL-17A, TNF-β, IL-1β, IL-2, IL-4, IL-6, IL-8, IL-10, IL-22, and IL-12p70, between the uninfected group and the pulmonary bacterial and fungal infection group (P < 0.05) was observed." (PMID 36319826, 2022). "These T cells produce cytokines including IL-4, IL-10 IL-17 and IFN-γ, which impair the fungal hyphae thus their reduction predisposes to secondary fungal infection." (PMID 35059222, 2022). "It has been reported that a number of major SNPs are associated with susceptibility of fungal infections and diseases, including MBL2, TLR1/4/6/9, CARD9, CXCL2, DECTIN1, IL4/10/15/2, and HLA." (PMID 33362211, 2020). "A similar enhancement in IL-4 was seen in a lung model of fungal infection when CCL7 was neutralized." (PMID 30671055, 2018). "Within affected sites only, IL-4 levels were significantly lower in bats displaying visible fungal infections characteristic of the syndrome." (PMID 23527062, 2013). "IL-4 was furthermore reported to be required for the induction of protective Th1 cell responses to fungal infections, such as Candida albicans." (PMID 22802978, 2012). "IL-4, in contrast, is a representative Th2 cytokine associated with non-protective or detrimental responses in fungal infections, often antagonizing IFN-γ activity." (PMID 41159718, 2025). "IL-4 and IL-13 can inhibit the differentiation and function of Th17 cells, potentially enhancing the Th17 response and subsequently developing unexpected dermatitis such as fungal infections or psoriasiform dermatitis." (PMID 40291282, 2025). "Aside from the expected resistance of both IL-4 and IL-13 against fungal species, IL-4 takes part in the optimal development of IL-12-dependent Th1 responses and IL-13 increases oxidative burst and phagocytosis during fungal infections." (PMID 38058517, 2023). "TLR ligands are classically considered to induce pro-inflammatory macrophage differentiation, and IL-4 cytokines are considered to induce anti-inflammatory macrophage differentiation, whereas dectin-1, a c-type lectin specific for β-glucans, induces fungal infection responses." (PMID 29483608, 2018). "Cytokines, such as IFN-γ, IL-12 and IL-4, are important proteins during fungal infection." (PMID 26091522, 2015). "The importance of developing a protective Th1/Th17 response over a nonprotective Th2 response in clearing fungal infections has been described previously, and the negative impact of IL-4 in macrophage activation during fungal infection is linked to fungal persistence." (PMID 28119468, 2017). "There were significant differences in IL-4, IL-6, IL-8, IL-10, IL-12p70, IL-1β, IL-2, TNF-β, IL-17, and IL-22 between the uninfected group and the pulmonary bacterial and fungal infection group (P < 0.05)." (PMID 36319826, 2022). "Meanwhile, anti-inflammatory cytokine IL-10 and type 2 cytokines (IL-4, IL-5, and IL-13) were similar in the WT or CD146 KO mice with fungal infection." (PMID 33537006, 2020). "Within the presented investigation leveling of IL-4 was shown to be comparable to IFN-γ, thus suggesting an activation of both, Th1 and Th2 cell-dependent pathways in response to invasive fungal infections." (PMID 28820494, 2017).
fungal infections (continued). "Within affected sites only, bats exhibiting visible fungal infections had significantly lower antioxidant activity and levels of IL-4 compared to bats without visible fungal infections." (PMID 23527062, 2013). "This may be attributed to the fact that, unlike dupilumab, tralokinumab does not inhibit IL-4 signaling pathways, making Th17 hyperactivation less likely and thereby reducing hyperactivated inflammation toward fungal infections." (PMID 40291282, 2025). "Furthermore, it has been recently shown that eosinophils produce IL-4 and therefore contribute to the development of the Th2 response, which is not considered protective in cases of fungal infections." (PMID 26700881, 2015). "Additionally, M1‐type cytokines, such as IL‐4, IL‐12, IL‐6, IL‐23, TNF‐α, IL‐1β, and IFN‐β, were slightly elevated upon stimulation by fungi, but no statistical difference was detected between the two fungal infection groups." (PMID 37211685, 2023).
leukemia (29 papers, 2013 to 2026). A malignant (clonal) hematologic disorder, involving hematopoietic stem cells and characterized by the presence of primitive or atypical myeloid or lymphoid cells in the bone marrow and the blood. "Alternatively, leukemia-derived DCs, i.e., leukemia cells differentiated in vitro toward a DC-like phenotype with GM-CSF, IL-4, TNF-α, and CD40L, are used." (PMID 41463107, 2025). "They observed the caspase signaling pathway were significantly enriched in leukemia cells treated with IL-4 compared with the untreated group." (PMID 37653079, 2023). "Our preclinical data using pharmacological approaches to inhibit IL-4 in combination with AraC treatment showed that targeting IL-4 represents a promising strategy to improve the therapeutic responses in leukemia." (PMID 36695938, 2023). "We also used an independent sample T test to compare the cytokines interleukin 4 (IL-4) and interleukin 10 (IL-10) between different groups of these 50 leukemia patients, which were obtained by flow cytometry as stated in the previous complaint." (PMID 35721208, 2022). "So we used flow cytometry to detect IL-4 and IL-10 in 50 leukemia patients, and compared their differences between different groups." (PMID 35721208, 2022). "This further confirmed the function of IL-4 in the sensitivity of leukemia cells to chemotherapeutic agents." (PMID 33321722, 2020). "It was recently reported that IL-4 is crucial during development of leukemia cell sensitivity to chemotherapeutic agents." (PMID 33321722, 2020). "The leukemia cells that expressed the Stat6 sgRNA had a selective proliferative advantage upon IL4 treatment and exhibited reduced apoptosis, demonstrating that IL4 depletes the leukemia cells in a Stat6-dependent manner by inducing apoptosis." (PMID 28819278, 2018). "The IL4 groups survived longer than the control groups, suggesting that IL4 inhibited leukemia-initiating cells." (PMID 28819278, 2018). "IL4 injections into mice engrafted with AML cells resulted in lower leukemia burden in both blood and bone marrow, accompanied by a significantly prolonged survival (median 26 versus 23 days, P<0.01)." (PMID 28819278, 2018). "At 2 weeks after transplantation, mice injected with IL4-secreting leukemia cells had elevated IL4 serum levels and reduced levels of leukemia cells in peripheral blood." (PMID 28819278, 2018). "We assessed the relationship between receptor expression levels and responses to each of the cytokines (IL-3, GM-CSF, IL-2, IL-4, M-CSF, G-CSF and IL-6) in leukemia cells from 11 patients with AML." (PMID 26375984, 2015). "Interestingly, IL-4 has two completely opposite effects in regulating mouse phagocytosis, it enhances macrophage-mediated killing of leukemia cells, but also induces CD47 expression, protecting target cells from excessive phagocytosis." (PMID 35721208, 2022). "The Il-4 pathway could also be crucial in the onset of leukemia via mechanisms unconnected to apoptotic dynamics." (PMID 32102441, 2020). "Moreover, we found that IL4 suppressed homing of the leukemia cells to the bone marrow as assessed 24 h post transplantation." (PMID 28819278, 2018). "To assess whether Stat6 disruption rendered the leukemia cells resistant to IL4, we monitored the percentage of sgRNA-expressing cells by tracking GFP+ cells during IL4 stimulation." (PMID 28819278, 2018). "To investigate whether the IL4-induced Stat6 activation was responsible for the depletion of leukemia cells, we first introduced ectopic Cas9 expression in the leukemia cells and sequentially a Stat6 sgRNA." (PMID 28819278, 2018). "We found that short exposure of leukemia cells to IL4 resulted in phosphorylation of Stat6." (PMID 28819278, 2018). "Next, we tested whether constitutive IL4 expression had a negative effect on AML cells also in vivo by transplanting sorted GFP+ leukemia cells secreting IL4 shortly after transduction." (PMID 28819278, 2018).
leukemia (continued). "To evaluate whether IL4 inhibits AML cells in vivo, we expressed IL4 ectopically in AML cells transplanted into mice and also injected IL4 into leukemic mice; both strategies resulted in the suppression of the leukemia cell burden and increased survival." (PMID 28819278, 2018). "These cells can inhibit the response of leukemia-specific CTLs to the malignant cells by secreting soluble factors including inhibitory cytokines, such as interleukin-4 (IL-4), IL-10, and transforming growth factor β (TGF-β), as well as chemokines CCL22, CCL17, and CCL5." (PMID 28116322, 2017). "Indeed, IFN-DC were found to be more effective than IL4-DC in priming cytotoxic anti-leukemia T cells." (PMID 28500302, 2017). "Our previous research discovered an excessive production of IL-4 by BM endothelial cells and found that this had a striking role in suppressing megakaryocyte differentiation in vivo, which might contribute to the thrombocytopenia of leukemia mice." (PMID 36695938, 2023). "In this study, seven cytokines (IL1β, IL4, IL6, IL8, GM-CSF, TNFα, and VEGF) were measured in neonatal blood spots from 1,020 ALL cases and 1,003 controls in the California Childhood Leukemia Study." (PMID 39658797, 2024). "THP-1 was a human leukemia monocytic cell line that had been extensively used to study macrophage functions, so we used PMA and IL-4/IL-13 to induce THP-1 cells into M2 phenotype macrophages in this study." (PMID 36641471, 2023). "In order to monitor similar changes in human leukaemia monocytic cell line, M1 and M2 status was induced in THP-1 cells by activation with LPS/INF-γ and IL-4/IL-13, respectively." (PMID 35884829, 2022). "The ratio of iNKT + IFN-γ+ to iNKT + IL-4+ was reduced in B-CLL patients, and this diminished as the leukemia advanced." (PMID 32102441, 2020). "For example, the combination of GM-CSF, IL-4, and TNFα induced the expression of MHC II, CD40, CD86, CD1a, CD1b, and CD1c by neutrophil-committed precursors isolated from leukemia patients receiving G-CSF treatments." (PMID 24278484, 2013). "IL-4 and IL-17A may be involved in ALL progression by promoting the proliferation of leukaemia cells and inhibiting apoptosis, and can also indirectly affect disease progression by modulating the tumor microenvironment." (PMID 41235219, 2025). "In human differentiated THP-1 cells (a human leukemia monocytic cell line), knockdown of PGAM5 stimulated TNFα and IL-6 secretion in naïve macropahges and increased TNFα, IL-6 and IL-1β in macropahges treated with IL-4 and IL-13 (M2 macrophage)." (PMID 37605246, 2023). "Unfortunately, in these 50 patients with leukemia, there was no significant statistical difference in the expression of cytokines IL-4 and IL-10 between different groups." (PMID 35721208, 2022). "In addition, GLA significantly reduced the release of histamine and β-hexosaminidase, calcium influx, cytokine (IL-4, TNF-α, IL-1β, IL-13, and IL-8) production in the RBL-2H3 (rat basophilic leukemia cells), and RPMCs (peritoneal mast cells) in vitro." (PMID 34007295, 2021). "Although IL-4 has shown antitumor effects and ALL cell suppression, it has been suggested that IL-4 expression in leukemia cells could reduce immunological recognition by decreasing HLA-class II molecule expression." (PMID 34867958, 2021). "In aggregate, these results proved that CSPG4-CAR T cells evince an antigen-specific secretion pattern of Th1 cytokines in response to KOPN8 leukemia cells, without IL-2 and IL-4 production." (PMID 31195686, 2019). "Validation experiments demonstrated that the negative effect of IL4 on leukemia cell expansion was observed even in the presence of cytokines such as IL3, which gives strong proliferative signals, and without NBM cells present." (PMID 28819278, 2018). "Following the identification of IL4 as a negative regulator of c-Kit+ AML cells in vitro, we next evaluated whether IL4 is also capable of inhibiting the growth and survival of leukemia-initiating cells." (PMID 28819278, 2018).
leukemia (continued). "c-Kit+MLL-AF9 leukemia cells were cultured ex vivo for 3 days with or without IL4, and then transplanted into sublethally irradiated recipient mice." (PMID 28819278, 2018). "Ex vivo IL4 treatment of leukemia cells suppressed the leukemia-initiating capacities of the cells, partially by inhibiting homing to the bone marrow, suggesting a negative effect of IL4 on LSCs." (PMID 28819278, 2018). "To explore the biological mechanism whereby IL4 exerts its negative effect on leukemia cells, we stimulated both c-Kit+MLL-AF9 AML and c-Kit+ NBM cells with IL4 and performed RNA sequencing." (PMID 28819278, 2018). "In our experimental setting, the FD leukemia supernatants did not block ex vivo differentiation of conventional myeloid DC (grown in the presence of GM-CSF and IL-4, results not shown)." (PMID 23616009, 2013). "However, because mice in the IL4 group at the time of killing did not have a fully developed leukemia, our data indicate poor tolerability of IL4 overexpression in vivo, potentially related to an expansion of T helper cells leading to aberrant cytokine secretion and splenomegaly." (PMID 28819278, 2018).